GHRH (growth hormone releasing hormone)
Description:
GRF is released by the hypothalamus and acts on the adenohypophyse to stimulate the secretion of growth hormone.
Synonyms: GRF; GHRF; INN
Tractability: Small molecule: a structure with a bound ligand is known. Antibody: its Gene Ontology location is reachable by antibodies, with high confidence; UniProt places it where antibodies can reach, with medium confidence; UniProt predicts a signal peptide or a membrane-spanning region.
Gene: Protein-coding gene on chromosome 20 (37,251,086 to 37,261,819, reverse strand). Ensembl gene ENSG00000118702.
Subcellular location: Secreted
Pathways (Reactome):
Signal Transduction: G alpha (s) signalling events; Glucagon-type ligand receptors
Gene Ontology:
Molecular function: growth hormone-releasing hormone activity; growth hormone-releasing hormone receptor binding; neuropeptide hormone activity; peptide hormone receptor binding; hormone activity; signaling receptor binding
Biological process: adenylate cyclase-activating G protein-coupled receptor signaling pathway; growth hormone secretion; multicellular organism growth; positive regulation of cell population proliferation; positive regulation of circadian sleep/wake cycle, REM sleep; positive regulation of growth hormone secretion; positive regulation of multicellular organism growth; adenohypophysis development; cell-cell signaling; positive regulation of cAMP/PKA signal transduction; positive regulation of insulin-like growth factor receptor signaling pathway; regulation of protein localization; response to food
Cellular component: extracellular region; perikaryon; terminal bouton
Genetic constraint (gnomAD): Loss-of-function variants: 5 observed, 11.37 expected, observed/expected ratio (o/e) 0.44, 90% interval 0.23 to 0.93. The upper end of that interval is the gene's LOEUF score, 0.93, which puts it in group 3 of 6, group 1 being the genes least tolerant of losing a copy. Missense variants: 104 observed, 129.09 expected, observed/expected ratio (o/e) 0.81, 90% interval 0.69 to 0.95. Synonymous variants: 50 observed, 49.5 expected, observed/expected ratio (o/e) 1.01, 90% interval 0.8 to 1.28.
Homologues: Orthologues: chimpanzee GHRH (98% identical), macaque GHRH (97% identical), pig GHRH (80% identical), dog GHRH (78% identical), guinea pig GHRH (72% identical), rabbit GHRH (68% identical), rat Ghrh (61% identical), mouse Ghrh (56% identical), zebrafish ghrh (31% identical). Paralogues in human: ADCYAP1 (31% identical), VIP (31% identical).
Diseases named in the same sentence as GHRH in open-access papers:
GHRH is named in the same sentence as 210 diseases in open-access papers, as found by Europe PMC text mining. Sharing a sentence is not in itself a finding about the gene and the disease. The quoted sentences say what the papers report.
acromegaly (51 papers, 2008 to 2026). Acromegaly is an acquired disorder related to excessive production of growth hormone (GH) and characterized by progressive somatic disfigurement (mainly involving the face and extremities) and systemic manifestations. "Acromegaly caused by ectopic growth hormone-releasing hormone (GHRH)-secreting neuroendocrine tumor (NET) is extremely rare, with cosecreting NETs even more seldom." (PMID 42007244, 2026). "There was a dramatic regression of facial features and pituitary lesion volume within 3 months after the removal of the lung NET, with near-normal GHRH and prolactin levels, implicating that the GHRH-secreting lung tumor caused the acromegaly." (PMID 39449742, 2024). "Hyperprolactinemia is likely attributable to increased GHRH, which is known to cause high prolactin in normal subjects and in patients with acromegaly, due to lactotroph hyperplasia." (PMID 39449742, 2024). "The term ‘ectopic acromegaly’ refers to a syndrome caused by secretion of growth hormone releasing hormone (GHRH), or occasionally, by an extra-pituitary source of GH and accounts for less than 1% of all acromegaly cases." (PMID 35757397, 2022). "GHRH was initially isolated from pancreatic tumours causing acromegaly, and later hypothalamic human GHRH was shown to be identical to the one isolated from pancreatic tumours." (PMID 36394485, 2022). "Michael Thorner, who isolated GHRH from a pancreatic tumour causing pituitary hyperplasia and acromegaly in the 1980s, emphasized that this experiment of nature demonstrates the vital importance of GHRH in addition to its role in growth." (PMID 36394485, 2022). "Ectopic acromegaly is a rare condition caused most frequently by growth hormone releasing hormone (GHRH) secretion from neuroendocrine tumors." (PMID 35757397, 2022). "Acromegaly caused by ectopic growth hormone-releasing hormone (GHRH)-secreting tumor is exceedingly rare." (PMID 34591404, 2021). "Exceptional examples of acromegaly/gigantism are caused by sellar tumors composed of hypothalamic GHRH-producing neurons, alone or associated with a sparsely granulated somatotroph tumor." (PMID 34067494, 2021). "In part the discovery of GHRH was made because ectopic GHRH secretion from human pancreatic islet tumors was seen to cause ectopic acromegaly by stimulating expression of GH." (PMID 34329319, 2021). "These tumors are generally associated to adenohypophysial pathology such as: acromegaly with impaired production of growth hormone-releasing hormone (GHRH), Cushing disease, precocious puberty and hyperprolactinemia." (PMID 32676456, 2020). "The most common cause of acromegaly is a pituitary tumor that causes excessive production of growth hormone (GH), and rare cases are due to an excess of the GH-releasing hormone (GHRH) or the ectopic production of GH." (PMID 31766255, 2019). "The majority have been associated with acromegaly and the production of GHRH but the other clinical manifestations of hormone excess include Cushing disease, hyperprolactinemia, and precocious puberty." (PMID 31635149, 2019). "Ectopic GHRH secretion, causing pituitary somatotroph hyperplasia, is a rare cause of acromegaly, responsible for less than 1% of cases." (PMID 31766255, 2019). "GHRH-secreting neuroendocrine tumours account for <1% of acromegaly, and the most common causative lesions are pancreatic or bronchial carcinoid." (PMID 24897038, 2014). "This is a report of the rare condition of a phaeochromocytoma co-secreting GHRH causing clinical and biochemical acromegaly." (PMID 24897038, 2014). "As previously discussed, acromegaly is rarely caused by ectopic tumors that produce GHRH (only 0.5% of acromegalic cases) or GH." (PMID 22518126, 2012). "Here, we present a case of ectopic acromegaly caused by a GHRH-secreting lung NET." (PMID 39449742, 2024). "Acromegaly caused by GHRH release is very rare disease, although one should be aware it exists." (PMID 35757397, 2022).
acromegaly (continued). "GHRH level above 250 ng/L indicates a high probability of an ectopic cause of acromegaly." (PMID 35757397, 2022). "In cases of the MEN1 syndrome, a GHRH-secreting pancreatic or thymic NET tumour might be part of the syndrome and the source of GHRH, which causes pituitary hyperplasia and thus acromegaly." (PMID 33543431, 2021). "Interestingly, the discovery of GHRH was due in part to the recognition of ectopic GHRH secretion from human pancreatic islet tumors causing ectopic acromegaly." (PMID 27777568, 2016). "In addition, acromegaly due to GHRH hypersecretion in carcinoid tumors is the most common cause, whereas paraneoplastic GH secretion is extremely rare in NET." (PMID 27349224, 2016). "In contrast, excess production of the GH-releasing hormone (GHRH) is an unusual but well documented cause of acromegaly, and may be associated with neuroendocrine tumors of lung, pancreas, thyroid (medullary thyroid cancer) or pheochromocytomas, as well as hypothalamic gangliocytomas." (PMID 31766255, 2019). "In addition, acromegaly caused by pituitary hyperplasia, either primary or due to ectopic GHRH, also has unique clinical and radiologic features, and may require a completely different therapeutic approach." (PMID 31766255, 2019). "Ectopic acromegaly occurs in cases of tumors which produce growth hormone-releasing hormone (GHRH) or extrapituitary tumors which produce GH." (PMID 38433543, 2024). "In another series of 21 cases, 5/21 cases of ectopic acromegaly due to GHRH with hyperprolactinemia were reported to have adenoma on imaging (4 macroadenoma and 1 adenoma not specified)." (PMID 39449742, 2024). "In a large review of ectopic GHRH secretion with acromegaly, 43 out of 96 cases were reported as pituitary enlargement, 20 as adenomas, 18 normal on imaging, 10 as unclear lesions, 3 as empty sellae, and 2 as microcystic lesions." (PMID 39449742, 2024). "After a left pneumonectomy, her clinical features of acromegaly improved, her diabetes underwent remission, and there was a marked reduction in plasma GHRH and pituitary size." (PMID 39449742, 2024). "A GHRH cutoff of 250–300 ng/l has been proposed to have a high specificity (93.8%) for the diagnosis of ectopic acromegaly, along with imaging." (PMID 39449742, 2024). "An excess incirculating GH and IGF-1, most commonly due to a pituitary adenoma and rarely dueto ectopic GH secretion or GHRH excess, leads to acromegaly." (PMID 39076279, 2023). "Definitive diagnosis of ectopic acromegaly requires confirmation of GHRH secretion from a tumor using either histopathological methods or GHRH plasma concentration assessment." (PMID 35757397, 2022). "In this article, 127 cases of ectopic acromegaly described after GHRH isolation in 1982 are comprehensively reviewed, along with a summary of current state of knowledge on its clinical features, diagnostic methods, and treatment modalities." (PMID 35757397, 2022). "A rare clinical situation of acromegaly due to ectopic GHRH production by PPGL (usually phaeochromocytoma) has also been described, including a MAX mutation positive case." (PMID 33805450, 2021). "In fact, it has been demonstrated that GHRH antagonists, such as MZ-4-71 and MZ-5-156, suppressed GH and IGF-I secretion in transgenic mice overexpressing human GHRH gene, an animal model of acromegaly." (PMID 34439107, 2021). "We report a case of acromegaly secondary to GHRH secretion by an incidentally diagnosed pulmonary neuroendocrine tumor (NET) and review 47 similar cases in literature." (PMID 34591404, 2021). "Pancreatic tumors can produce GHRH resulting in acromegaly; this observation was made possible by the isolation and characterization of GHRH." (PMID 33096674, 2020). "It has been proposed that hyperplastic change can precede adenomatous transformation in human patients, and somatotroph hyperplasia has been shown to result in somatotroph adenoma formation in GHRH-overexpressing mice." (PMID 30620005, 2019).
acromegaly (continued). "In rare scenarios, Cushing syndrome and acromegaly from the overproduction of adrenocorticotropic hormone and growth hormone-releasing hormone respectively, are observed as well." (PMID 30545054, 2018). "Five patients had acromegaly secondary to ectopic growth hormone-releasing hormone (GHRH) secreting tumors." (PMID 28733467, 2017). "Co-existance of acromegaly due to GHRH-secreting neuroendocrine tumor and a prolactinoma has also been described in MEN1 syndrome, representing a significant diagnostic challange." (PMID 28161730, 2017). "In these tumors, paraneoplastic syndromes have been described to drive the course of the disease, among them acromegaly induced by paraneoplastic secretion of growth hormone-releasing hormone (GHRH)." (PMID 27349224, 2016). "Non-pituitary tumors such as small-cell lung cancer, adrenal adenoma, medullary thyroid carcinoma or pheochromocytoma or pancreatic neuroendocrine tumors can lead to acromegaly by production of growth hormone–releasing hormone (GHRH)." (PMID 27349224, 2016). "This is a report of the rare condition of a phaeochromocytoma co-secreting GHRH resulting in clinical and biochemical acromegaly." (PMID 24897038, 2014). "Ectopic acromegaly due to a GHRH neuroendocrine tumor (NET) should be suspected when a patient presents with all the clinical and biochemical features of the disease but without evidence of a pituitary adenoma on MRI." (PMID 24119925, 2013). "In less than 2% of the cases, acromegaly results from GHRH-secreting neuroendocrine tumors usually located in the lungs, thymus and endocrine pancreas." (PMID 24119925, 2013). "Excessive production of GHRH from central hypothalamic sources (usually gangliocytomas) or peripheral sources can lead to somatotroph hyperplasia and acromegaly." (PMID 22518126, 2012). "Pancreatic GHRHoma is MEN1 related in about 10% of cases; it is characterized by elevated serum concentrations of growth hormone and growth hormone releasing hormone (GHRH), and the patients result affected with acromegaly." (PMID 24213321, 2012). "Very rarely acromegaly is due to hypothalamic over secretion of growth hormone releasing hormone (GHRH) or to extra-pituitary tumours that secrete GH or GHRH." (PMID 19814797, 2009). "In very rare cases, acromegaly is due to ectopic secretion of growth-hormone-releasing hormone (GHRH) responsible for pituitary hyperplasia." (PMID 18578866, 2008). "The lack of clear signs of an adenoma on MRI, or an appearance showing a bulging, hyperplastic pituitary, suggests that the acromegaly is secondary to ectopic GHRH secretion." (PMID 18578866, 2008). "In addition, secretion of growth hormone‐releasing hormone (GHRH) from a hypothalamic adenoma or ectopic GHRH production from neuroendocrine tumors in the lungs or pancreas can also contribute to acromegaly." (PMID 40190357, 2025). "It should be noted that, in MEN1 patients, GH excess and subsequent acromegaly may instead derive from ectopic growth hormone releasing-hormone (GHRH) secretion by neuroendocrine pancreatic tumours." (PMID 37891382, 2024). "Acromegaly due to ectopic secretion of growth hormone-releasing hormone (GHRH) is a rare disorder." (PMID 39449742, 2024). "Inpatients with biochemically confirmed acromegaly with a normal pituitary MRI,further testing with GHRH measurement, somatostatin receptor scintigraphy, andthoracic or abdominal imaging may be considered." (PMID 39076279, 2023). "Furthermore, the role of GHRH antagonists of JV series in blocking GHRH actions was described in the same in vitro model of somatotroph adenoma used in this study, i.e., rat pituitary GH3 cells that were induced to express a functional human GHRH-R." (PMID 34439107, 2021). "Acromegaly associated with phaeochromocytoma can be the consequence of a GHRH-secreting phaeochromocytoma without any pituitary adenoma." (PMID 33543431, 2021).
acromegaly (continued). "While most cases are secondary to a GH-secreting pituitary adenoma, acromegaly may rarely be secondary to a hypothalamic secreting GH-releasing hormone (GHRH) or ectopic GHRH or GH secretion." (PMID 33803429, 2021). "Moreover, some investigations have demonstrated that GHRH can synthesize not only in the normal pituitary gland, but also concurrently in somatotroph adenoma cells." (PMID 32706866, 2020). "Ectopic acromegaly is rare, and since the discovery of GHRH, few cases have been reported." (PMID 33096674, 2020). "Depending on the hormonal product of the hypothalamic tumor, patients may have acromegaly due to excess GHRH, Cushing disease due to CRH excess, or even low levels of vasopressin excess or significant hyperprolactinemia." (PMID 31635149, 2019). "In summary, the case presented here is an extremely rare example of a sporadic pulmonary NET associated with GH and IGF-1 but not GHRH secretion, thereby inducing a clinically florid acromegaly." (PMID 27349224, 2016). "Interestingly, mice transgenic for GHRH develop mammosomatotroph hyperplasia, and occurrence of somatotroph adenomas has been described in older animals." (PMID 27245663, 2016). "Notably, adenomatous transformation to a SG somatotroph adenoma was reported in a case of pituitary hyperplasia and ectopic acromegaly due to a pituitary metastasis from a GHRH-secreting neuroendocrine tumor." (PMID 27245663, 2016). "One patient had acromegaly due to a GHRH-secreting pheochromocytoma." (PMID 25494863, 2015). "It is debatable whether the patient’s clinical picture and biochemical evidence of acromegaly were the result of GHRH secretion from the suprasellar craniopharyngioma." (PMID 20864785, 2010). "In rare instances, NETs may induce acromegaly through ectopic secretion of GHRH." (PMID 41573472, 2025). "Acromegaly is a chronic disease caused by the increased release of growth hormone (GH) and accompanying insulin-like growth factor I (IGF-1); in most cases, this is induced by a GH-secreting pituitary adenoma and rarely results from ectopic growth-hormone-releasing hormone (GHRH) or GH secretion." (PMID 36983284, 2023). "In patients with acromegaly and MEN1 syndrome, GHRH-secreting pancreas tumours should be considered." (PMID 33805450, 2021). "In rare cases, they can present with Cushing syndrome and acromegaly due to the overproduction of adrenocorticotropic hormone (ACTH) and growth hormone-releasing hormone (GHRH), respectively." (PMID 32923302, 2020). "Hyperprolactinemia is not uncommon but is rarely in the tumoral range in GHRH-secreting ectopic acromegaly." (PMID 39449742, 2024). "PNET secretion of growth-hormone releasing hormone (GHRH) and adrenocorticotropic hormone (ACTH) have been reported in the literature, with patients presenting with the characteristic symptoms of acromegaly and Cushing syndrome, respectively." (PMID 37046665, 2023). "For example, it has been shown that senescent cells in somatotroph adenomas also secrete growth hormone (GH) as part of their SASP and that GH and growth hormone releasing hormone (GHRH) are inducers of DNA damage and genomic instability in normal pituitary cells." (PMID 34019103, 2021). "Previous studies demonstrated the ability of earlier GHRH antagonists, MZ-4-71 and JV-1-36, to inhibit GH secretion induced by GHRH in somatotroph adenomas, an experiment not performed here because of the paucity of tumor samples." (PMID 34439107, 2021). "Possible coexistence of acromegaly due to pancreatic GHRH excess and prolactin-secreting or non-functioning pituitary tumour remains a diagnostic challenge in MEN1 patients." (PMID 33805450, 2021). "In case of acromegaly confirmation without a pituitary adenoma or pituitary hyperplasia, plasma growth hormone-releasing hormone (GHRH) must be requested to rule out a secreting neuroendocrine tumor." (PMID 34557164, 2021).
acromegaly (continued). "There is a case of acromegaly attributed to GHRH production by such a tumor, and some have had no features of hormone production." (PMID 31635149, 2019). "In MEN1 patients with acromegaly and enlarged pituitary gland with no discernable pituitary adenoma, a GHRH-secreting neuroendocrine tumor, typically arising from the pancreas should also be considered." (PMID 28161730, 2017). "Laboratory tests revealed markedly increased growth hormone (GH) and insulin-like growth factor 1 (IGF-1) without GHRH elevation in the absence of pituitary pathologies confirming the paraneoplastic origin of clinical presentation with acromegaly." (PMID 27349224, 2016). "Neuroendocrine tumours can stain positive for GHRH without coexisting acromegaly, but the resolution of patient symptoms and normalisation of serum GH and IGF1 levels following surgery imply that this was functional secretion." (PMID 24897038, 2014). "However, both hypersecretion of growth hormone-releasing hormone (GHRH) and growth hormone (GH) may lead to acromegaly." (PMID 27349224, 2016). "Point mutations in GNAS and other genomic and nongenomic aberrations in the tightly regulated GHRH-GHRHR signaling pathway result in persistent cAMP signaling, inducing GH production and somatotroph proliferation, and potentially favoring the development of sporadic somatotroph adenomas." (PMID 41824769, 2026).